ZNF114 (zinc finger protein 114)
Description:
May be involved in transcriptional regulation.
Synonyms: MGC17986
Tractability: No criterion of Open Targets' tractability assessment is met for any kind of drug.
Gene: Protein-coding gene on chromosome 19 (48,270,041 to 48,287,743, forward strand). Ensembl gene ENSG00000178150.
Subcellular location: Nucleus
Subcellular location (Human Protein Atlas): Cytosol; Nucleoplasm
Pathways (Reactome):
Gene expression (Transcription): Generic Transcription Pathway
Gene Ontology:
Molecular function: identical protein binding; protein binding; DNA-binding transcription factor activity, RNA polymerase II-specific; RNA polymerase II cis-regulatory region sequence-specific DNA binding
Biological process: regulation of DNA-templated transcription; regulation of transcription by RNA polymerase II
Cellular component: extracellular exosome; nucleus
Genetic constraint (gnomAD): Loss-of-function variants: 8 observed, 7.52 expected, observed/expected ratio (o/e) 1.06, 90% interval 0.62 to 1.77. That is too few expected variants to judge how well the gene tolerates losing a copy. Missense variants: 472 observed, 548.29 expected, observed/expected ratio (o/e) 0.86, 90% interval 0.8 to 0.93. Synonymous variants: 169 observed, 194.94 expected, observed/expected ratio (o/e) 0.87, 90% interval 0.76 to 0.99.
Homologues: Orthologues: chimpanzee ZNF114 (98% identical), macaque ZNF114 (91% identical). Paralogues in human: ZNF92 (33% identical), ZNF66 (33% identical), ZNF98 (33% identical), ZNF737 (32% identical), ZNF430 (32% identical), ZNF723 (32% identical), ZNF253 (31% identical), ZNF680 (31% identical), ZNF675 (31% identical), ZNF626 (31% identical), ZNF431 (31% identical), ZNF257 (30% identical), and 6 more.
Diseases named in the same sentence as ZNF114 in open-access papers:
ZNF114 is named in the same sentence as 2 diseases in open-access papers, as found by Europe PMC text mining. Sharing a sentence is not in itself a finding about the gene and the disease. The quoted sentences say what the papers report.
colon cancer (1 paper, 2024). "It has been reported that CD22 functions as a regulator of B-cell response and is associated with oxaliplatin resistance in colon cancer, while ZNF114 potentially promotes non-small cell lung cancer (NSCLC) metastasis." (PMID 37934338, 2024).
ZNF114 also shares sentences with these, for which no sentence is quoted: non-small cell lung carcinoma (1 paper).